IL6 (interleukin 6)
Diseases named in the same sentence as IL6 in open-access papers (continued):
Sharing a sentence is not in itself a finding about the gene and the disease.
breast cancer (continued). "Silencing GRN also reduced experiments because it induces robust stimulation of IL-6 and OSM-induced STAT3 transcriptional activity as STAT3 tyrosine phosphorylation and is physiologically measured by luciferase reporter assay, indicating that this relevant in breast cancer cell proliferation." (PMID 26000098, 2015). "In addition, the FN1, IL6 and FOS genes were found to be involved in breast cancer development." (PMID 25824986, 2015). "Consistent with our cell line study, IL6 expression was significantly correlated with YAP/TAZ expression in BLBC, but not in luminal-type breast cancer, indicating that IL6 could be a BLBC-specific transcriptional target of YAP." (PMID 26671411, 2015). "The FN1, IL6 and FOS genes may therefore be potential targets in the treatment of breast cancer." (PMID 25824986, 2015). "Likewise, IL-6 promotes EMT in breast cancer cells, and SNAIL can induce IL-6 expression." (PMID 24606538, 2014). "IL-11, a pleiotropic cytokine of the interleukin-6 type family, has been chosen as the “indicator” gene to investigate down-stream TGF-β signaling pathways, as reported for lung fibroblasts, periodontal ligament and gingival fibroblasts, and bone metastatic breast cancer cells." (PMID 25197981, 2014). "To focus on cytokines and growth factors specifically produced by ASCs (EGF, FGF, HGF, SDF, IL6, IL8, IL10) or epithelial breast cancer cells (EGF, FGF, HGF) known to be relevant in tumorigenesis, we carried out Q-PCR analyses both on ASCs or primary breast cancer cells, before and after co-culture." (PMID 24327602, 2014). "Additionally, in breast cancer cell lines, non-canonical Notch signaling is known to regulate IL-6 expression, and IL-6, in turn, acts on tumor cells to further increase their oncogenic potential." (PMID 25538890, 2014). "Specifically, serum levels of IL-6 independent of activity, predict poor outcome in breast cancer." (PMID 23840733, 2013). "Thus, neither repeated transfer of splenic MDSCs from metastatic tumor-bearing mice nor overexpression of IL-6 was sufficient to confer on non-metastasizing EMT6 cancer cells a metastasizing capacity comparable to that of 4T1 breast cancer cells." (PMID 24021059, 2013). "The contact of breast cancer cell lines with the microenvironment completely modified their transcriptional programs by increasing the expression of genes involved in cell proliferation (cyclinD1, MAPK), angiogenesis (MMP9, VEGF) and hormonal pathways (ESR1, IL6)." (PMID 23750285, 2013). "In breast cancer cell lines, IL-6 converts non-stem cancer cells into CSCs." (PMID 22472196, 2012). "Astrocytes have been shown to produce a wide variety of cytokines and growth factors; among them, it was suggested that IL-6, TNF-α and IL-1β may contribute to the development of brain metastasis by lung cancer cells, and IL-6, TGF-β and IGF-1 by breast cancer cells." (PMID 23271367, 2012). "We provide evidence that TG2 is an important link in IL-6-mediated tumor aggressiveness, and that TG2 could be an important mediator of distant metastasis, both in a xenograft animal model and in patients with advanced breast cancer." (PMID 21967801, 2011). "Furthermore, by using public datasets that included a total of 684 breast cancer patients, we found that the expression of TG2 and IL-6 was correlated in breast cancer patients and that the combined high expression of TG2 and IL-6 was related to a poor DMFS outcome in breast cancer." (PMID 21967801, 2011). "Some breast cancer cells neither expressed TG2 nor produced IL-6." (PMID 21967801, 2011). "This indicates that IL-6 is not the downstream mediator of IL-1β-mediated MDSC infiltration in the 4T1 breast cancer model, and suggests that another downstream target of IL-1β may modulate MDSC infiltration in this model." (PMID 19888452, 2009).
breast cancer (continued). "If IL-6 is the major factor contributing to this enhanced growth, then the much higher production of IL-6 by MDA-MB-231 breast cancer cells versus MDA-MB-468 breast cancer cells would account for the lack in enhanced cell proliferation effect in MDA-MB-468 breast cancer cells." (PMID 18939993, 2008). "Understanding how IL-6 and other soluble factors are involved in this paracrine activation of STAT3 via the tumor microenvironment may provide new therapeutic insight to treat breast carcinomas and other cancers with elevated p-STAT3 and IL-6 levels." (PMID 18939993, 2008). "Surprising specificity of LY294002 in inhibiting IL-6 but not TRAF-1 expression is encouraging as inhibitors with similar properties can be used to reduce invasion of breast cancer cells, more so of ERα-positive cancer cells, by specifically reducing IL-6 expression." (PMID 14970864, 2004). "Our results revealed that rosuvastatin can protect against cardiotoxicity associated with breast cancer therapy especially doxorubicin and trastuzumab documented by LVEF and proved by specific cardiac inflammatory marker, hs-cTnI and non-specific markers, MPO and IL-6." (PMID 38977536, 2024). "In both breast cancer cell lines in this study, lunasin regulated ERα/β genes and the aromatase gene and its activity at 24 h, indicating that this suppressive property might not be dependent on the IL-6 pathway." (PMID 36794014, 2023). "Moreover, oncogenic miR-183-5p in breast cancer-derived EVs are engulfed by macrophages and downregulate target gene PPP2CA expression by combining with the binding sequence which leads to a decrease in dephosphorylation of p65, consequently promoting IL-1β, IL-6, and TNF-α secretion." (PMID 36405712, 2022). "However, the addition of IL-6 did not upregulate M1-associated genes in MCF-7-induced TAMs, suggesting that multiple mediators contribute to the complexity of macrophage polarization induced by breast cancer." (PMID 35960749, 2022). "Since IL-6Rα and gp130 are required for signal transduction, the previous contradictory results may have been attributed to a lack of receptor expression in tested breast cancer cell lines, or that IL-6’s pleiotropic effects may depend on JAK/STAT3 pathway activation." (PMID 35371975, 2022). "Probable mechanisms by which ASCs might increase the metastatic capacity of breast cancer cells include initiation of EMT, matrix degradation through elevated expression of MMPs, induction of angiogenesis, and secretion of paracrine factors favoring metastatic spread, PDGF-D, IL-6, and IL-8." (PMID 36077676, 2022). "Moreover, targeting STAT3 in human breast cancer cells was reported to suppress the tumor progression by regulating the expression of crucial proteins in tumor milieu, such as survivin, chemokines (CCL5 and CXCL10) and proinflammatory cytokines (IL-6, IL-5, TNF-a, and IFN-γ)." (PMID 33957948, 2021). "In addition, since we lacked information on CRP or IL-6, further studies with these markers may shed light in the LIPG-breast cancer association." (PMID 34001944, 2021). "Moreover, IL-6 has been linked to Lin28/Let7 signalling, where NFKB-activated Lin28 inhibits Let7, leading to increased IL-6 levels and consequent NFKB activation, enforcing a positive feedback loop that contributes to the generation and maintenance of CSC-like populations in breast cancer." (PMID 34361105, 2021). "There are reports that chronic stress could induce a microenvironment with an enhanced expression of inflammatory factors, such as TNF-α, IL-1, IL-6, and IL-8, which are believed to play a role in malignant tumor progression and negative prognosis in cancers, including breast cancer." (PMID 34485118, 2021). "As previous study has reported that blocking of STAT3 in breast cancer cells induced an antitumor immune response involving CD4+ T cells, which may ameliorate TME via secretion of cytokines, such as TNF-α, IFN-γ, IL-6, and IL-5, as well as chemokines CCL5 and CXCL10." (PMID 33957948, 2021).
breast cancer (continued). "For instance, interleukin-6 (IL-6) is sufficient for converting non-CSCs to CSCs in different breast cells, and IL-6 regulates the conversion of non-CSCs into CSCs, activating the Notch-3-dependent upregulation of the Notch ligand Jagged-1 in breast cancer cells." (PMID 32977636, 2020). "Moreover, Faecalibacterium prausnitzii, the most well-known species in Faecalibacterium genus, could inhibit the secretion of interleukin-6 (IL-6) and the phosphorylation of Janus kinases 2 (JAK2)/signal transducers and activators of transcription 3 (STAT3) in breast cancer cells." (PMID 32272885, 2020). "Hence, paracrine IL-6 signalling maybe a key regulatory pathway by which adipocytes induce EMT and promote proliferation, migration and invasion in both luminal (MCF-7) and basal (MDA-MB-468) breast cancer cells." (PMID 29891854, 2018). "Combining this observation with our results showing that IL-6 enhances PLOD2 expression in the short term, we hypothesized that adipocyte coculture would increase PLOD2 expression in the short term and maintain this expression in the long term in breast cancer cells." (PMID 30563531, 2018). "Thus, ATR-II abated proinflammatory cytokines (TNF-α and IL-6), reduced oxidative markers (MDA and 8-OH-dG) and increased GSH/GSSG ratio in the mammary glands, which suggested that ATR-II had anti-inflammatory and antioxidant activities in the NMU-induced rat breast cancer model." (PMID 29100404, 2017). "However, the proportion of breast cancers sensitive to anti-IL-6 therapies is not known." (PMID 27602583, 2016). "Therefore, to find a mechanistic basis of placental KP-modulation of breast cancer cells vital parameters, we next examined whether or not production of IL-6 and IL-8 are affected by placental KPs." (PMID 27101408, 2016). "Additionally, the IL-6-induced CD44+ cells exhibited increased resistance to radiation, and reduced cell death after doxorubicin treatment compared with CD44− cells, which was consistent with the characteristics of breast cancer stem cells (BrCSCs) reported in previous studies." (PMID 22134360, 2012). "Moreover, IL-6 autocrine loop could trigger a Notch-3/Jagged-1 pathway to enhance the growth and aggressive phenotypes of mammospheres derived from malignant mammary tissue or MCF7 breast cancer cell line." (PMID 22023707, 2011). "Thus, TG2 expression in cancer cells is an important link in IL-6-mediated tumor aggressiveness, and TG2 could be an important mediator of distant metastasis, both in a xenograft animal model and in patients with advanced breast cancer." (PMID 21967801, 2011). "Thus, in this study, we provide evidence that TG2 is an important link in IL-6-mediated tumor aggressiveness and that TG2 could be an important mediator of distant metastasis in both a xenograft animal model and in patients with advanced breast cancer." (PMID 21967801, 2011). "Unlike IL-6 or IL-1, there have been few, if any, clinical trials specifically testing anti-TNF agents (such as infliximab or etanercept) in breast cancer patients." (PMID 41007766, 2025). "This study, through a systematic review and meta-analysis, examined the outcomes of 19 articles that classified breast cancer based on the presence or absence of specific biomarkers (ER, PR, HER2, IL-6, TNF-alpha)." (PMID 40558287, 2025). "Christodoulatos et al186 discovered an independent negative correlation between plasma omentin-1 levels and breast cancer incidence in a postmenopausal cohort and inflammatory markers (TNF-α, IL-6)." (PMID 40584290, 2025). "In a molecular mechanism study exploring the link between sleep and breast cancer, a positive correlation was identified between TGF-β and CRP levels and insomnia, while IL-6 showed a negative correlation with sleep-inducing medications." (PMID 38919616, 2024). "The signature profile analysis of CXCL8, IL6, and NFKB1 revealed a higher mRNA expression in non-responder breast cancer patients (p = 0.015)." (PMID 39336151, 2024).
breast cancer (continued). "CXCL8 (p = 0.12), IL6 (p = 0.022), and NFKB1 (p = 0.0097) mRNA levels were higher in breast cancer patients who did not respond to chemotherapy treatment." (PMID 39336151, 2024). "Therefore, blocking IL-6 (i.e., anti-IL-6 therapy), targeting its receptor in combination with signaling from other anticancer therapies, and targeting the IL-6-STAT3 axis is a potential therapeutic strategy that may be beneficial in the treatment of breast cancer." (PMID 36835413, 2023). "In ERα-negative breast cancer cells, CAF-secreted IL-6 decreases c-MYC expression and suppresses tumor growth." (PMID 36721232, 2023). "Several of the immune genes were expressed at a significantly lower level in the resistant than sensitive mammary tumors in the HFD offspring not treated with genistein: Foxp3 (p = 0.012), Tgfb1 (p < 0.001), Ctla4 (p = 0.023) and Il6 (p = 0.018)." (PMID 33440675, 2021). "We chose these breast cancer cells in particular because MCF7 cells are less aggressive and do not constitutively express IL6 or IL8." (PMID 33868586, 2021). "Indeed, in breast cancer, ATP stimulation on the P2Y2 receptor could induce chemoresistance towards a variety of chemotherapeutic agents, including cisplatin, doxorubicin, paclitaxel, and gemcitabine, via indirect activation of IL-6 to trigger its downstream JAK-1-SOX9 signaling." (PMID 34833046, 2021). "Considering the lack of knowledge, feline serum VISTA levels from cats with mammary carcinoma were compared with healthy controls, and with serum levels of PD-1/PD-L1, CTLA-4, LAG-3, IL-6, and TNF-α." (PMID 34771722, 2021). "While OSM, LIF, and IL-6 can induce STAT3, AKT, and ERK signaling in breast cancer cells, in the absence of studies using combinations of STAT3, AKT, and ERK inhibitors, it is difficult to determine which is the dominant downstream mediator." (PMID 32023849, 2020). "This study aimed to investigate cytokine mRNA expression levels of IL-6, IL-18, TNF-α, and CRP in hepatocytes from breast cancer xenograft mice with or without moderate exercise." (PMID 32309219, 2020). "First, breast cancer patient serum had significantly higher levels of OSM and IL-6 compared to serum from individuals without malignancies." (PMID 31007849, 2019). "Our new in vivo evidence suggests bone metastatic breast cancer cells induce a non-normal osteoblast state of osteopontin (OPN) high, alpha-smooth muscle actin (aSMA) low, and IL-6 low." (PMID 30813947, 2019). "Non-breast cancer, estrogen receptor-negative cell lines were also tested for OSM-induced IL-6 secretion, including PC3 and DU145 human prostate cancer cells, as well as HeLa human cervical carcinoma cells." (PMID 31007849, 2019). "In this context, IL-6, G-CSF, and MCP-1 were enriched in WHF from patients with invasive versus in situ breast cancer, independent of the extent of the surgery." (PMID 30791501, 2019). "Despite it has been demonstrated that both IL-6 and RANTES favor breast cancer proliferation and migration, the effects of the simultaneous overexpression of RANTES and IL-6 on breast cancer cells’ phenotype have not been explored." (PMID 29707128, 2018). "Previous work has shown that fibroblast-derived SASP induced a classic EMT in two human non-aggressive luminal breast cancer cell lines T47D and ZR75.1 and that this effect was principally exerted through IL6 and IL8 secretion." (PMID 28472950, 2017). "Significantly higher values of RANKL, CTKS, PTH1R, IL-6, IL-1β and MMP-1 were found in bone fragments cultured with MCF-7 breast cancer cells in comparison to bone fragments cultured without cancer cells, both in normoxic and hypoxic conditions." (PMID 27765913, 2016). "Our previous study showed that long-term treatment of lapatinib in breast cancer cells with or without HER2 expression enhances NF-κB activation and subsequently results in the expression of NF-κB downstream genes, including IL6." (PMID 27694691, 2016).
breast cancer (continued). "The over-expressed CCNE1, CLGN, NEK2, PTTG1 and RAD51, and the under-expressed ADAMTS1, FOS, FOSB, IL6 and ZFP36 in tumor cells are examples of breast cancer genes without differential promoter methylation between normal and tumor samples." (PMID 25706888, 2015). "IL-6, MCP-1, and TNFα are elevated in mouse wound healing models but not in this breast cancer model, except for IL-1β, elevated in both models." (PMID 26113869, 2015). "Although it has been reported that IL-6 and its downstream signal mediator, STAT3, can increase Twist expression through transcription in breast cancer cell lines, this does not exclude the mechanism of post-translational modification of Twist expression." (PMID 21559372, 2011). "Like estrogen receptor alpha (ERα)—positive breast cancer cells, on which we have previously reported, our MSC-enhanced Skov-3 growth relies on MSC-secreted paracrine factors, such as IL-6, and not strictly on cell-cell contact." (PMID 19352430, 2009). "Previously, we reported constitutive NF-κB activation in the ERα-negative breast cancer cell line MDA-MB-231, which correlated with increased expression of several NF-κB-inducible genes including IL-6, Mn-SOD, cIAP-2 and TRAF-1." (PMID 14970864, 2004). "Using the ERα-negative breast cancer cell line MDA-MB-231 stably overexpressing ERα, we show that ERα transrepresses tumour necrosis factor alpha (TNFα)-inducible expression of IL-6." (PMID 14970864, 2004). "A study has shown that circulating levels of A-FABP, also known as FABP4, are significantly higher in obese patients with breast cancer than in those without breast cancer, and circulating A-FABP enhances tumor stemness and aggressiveness by activating the IL-6/STAT3/ALDH1 pathway." (PMID 37056351, 2023). "A study of 105 breast cancer patients showed that IL-10 expression was higher in patients with higher ER negative and SBR classification; higher serum IL-6 levels were more common in triple negative breast cancer (TNBC) patients and used to monitor predictive therapeutic response." (PMID 36693957, 2023). "Nevertheless, IL6 treatment of MCF‐7 cells did not induce NED, suggesting either that factors inducing NED in breast and prostate cancer cells are different or that breast cancer cells are less permissive and need additional SASP factors to undergo NED." (PMID 35653631, 2022). "However, zebrafish are not mammalian, so some important pathways in breast cancer tumor development are absent, including BRCA1, p16 (CDKN2A), Leukemia Inhibitory Factor (LIF), oncostation M (OSM) and interleukin 6 (IL6)." (PMID 34123857, 2021). "Serum samples collected before and after the exercise training intervention provided evidence of a reduction in systemic inflammation shown by lower IL-6 and TNF-alpha post-intervention, but these serum samples had no anti-growth effect on the breast cancer cell lines." (PMID 33597950, 2020). "In contrast to nontreated con cells, for senescent human breast cancer MDA-MB-231 cells, the factors detected by arrays and secreted at a significant level are FGF-6, GM-CSF, IGFBP-1, MCP-1, IL-6, IL-1α, GRO a/b/g, GRO α, IL-8, MIP, MIP-1α, uPAR, ICAM-1, and MMP-1." (PMID 30871042, 2019). "Interleukin 6 (IL6) was discovered to induce the conversion of non-BCSCs into BCSCs by activating OCT4 transcription through STAT3, thereby increasing the self-renewal activity of breast cancer cells." (PMID 31324052, 2019). "However, the contributions and mechanisms of IL-6 on the EMT and stemness of breast cancer have not been fully elucidated." (PMID 30989585, 2019). "Indeed, mRNA analysis has also confirmed IL-6 receptor expression in IBC cells [73, Morrow unpublished observations], and IL-6/STAT3 signaling has been proposed to underpin the dynamic equilibrium between stem and nonstem breast cancer cells." (PMID 28607534, 2017).